IRF9 (interferon regulatory factor 9)
Diseases named in the same sentence as IRF9 in open-access papers (continued):
Sharing a sentence is not in itself a finding about the gene and the disease.
cancer (40 papers, 2009 to 2025). A tumor composed of atypical neoplastic, often pleomorphic cells that invade other tissues. "Deficiencies of IRF9 lead to a significantly greater risk of severe COVID-19 illness and impair cancer-protective effects of BRCA2 gene activity." (PMID 37626783, 2023). "IRF9 signaling has been implicated in the epithelial–mesenchymal transition, a hallmark of cancer metastasis, suggesting that it could facilitate cancer progression." (PMID 39791702, 2024). "IL33 was found to have widespread positive correlations in several cancer types, whereas IRF9 and TRAF5 demonstrated more heterogeneous correlation profiles." (PMID 40893939, 2025). "Specifically, we revealed that FAT1 can phosphorylate CaMKII and further impede the formation of the p-STAT1/IRF9 complex, thereby exerting its role in suppressing cancer." (PMID 39781458, 2025). "The results revealed that the overexpression of STAT1 or IRF9 alone inhibited the stemness of cancer cells and that the co-overexpression of STAT1 and IRF9 strongly suppressed cancer stemness." (PMID 39781458, 2025). "Cancer cells harboring the unphosphorylated STAT1/unphosphorylated STAT2/IRF9 complex are more resistant to DNA damage-inducing chemotherapy than those lacking the complex." (PMID 38474078, 2024). "In conclusion, this study underscores the significance of changes in IRF9 expression among various IRFs/STATs in relation to drug responsiveness, which is applicable across cancer types both in vitro and in vivo." (PMID 39062738, 2024). "This research broadens our understanding of the complex role of type I IFN signaling in cancer by identifying IRF9 as a key regulator of therapeutic responses." (PMID 39062738, 2024). "IRF9 suppression is also expected to impair the cancer-protective effects of BRCA2 and has been found to promote a powerful immunoinflammatory response associated with lethal neurological disease." (PMID 37626783, 2023). "Other than as a subunit in the ISGF3, IRF9 also regulates many other cellular processes that are related to the pathogenesis of diseases including cancer, cardiovascular, and inflammatory diseases." (PMID 36691924, 2023). "Work in both normal and cancer cells demonstrated that IRF9 can assemble with unphosphorylated STAT1 and STAT2 to form the unphosphorylated ISGF3 (U-ISGF3) complex." (PMID 35244540, 2022). "Among the enriched CCs, The cytoplasm (associated with 6 KGs: OAS1, OAS3, IRF9, HPGD, TP53INP1 and NQO1) has been found to be associated with most proteins that are highly expressed for cancer." (PMID 35617355, 2022). "Overall, these findings will be important to inform the development of therapeutic strategies to improve outcomes for patients with this deadly cancer and other diseases where the IRF9-mediated production of IL-6 can be therapeutically modulated." (PMID 35205671, 2022). "Chromatin immunoprecipitation (ChIP) sequencing data from the University of California, Santa Cruz (UCSC) genome browser indicated that STAT3 binds to the IRF9 promoter near the transcription start site in multiple cancer cell lines." (PMID 30679726, 2019). "The control tumors contained higher percentages of mouse stromal cells, while the IRF9 knockdown tumors were mostly comprised of cancer cells." (PMID 30355451, 2018). "The cancer cells in tumors with IRF9 knockdown had a slight but insignificant increase in Ki67 staining, a marker for cell proliferation, over cancer cells in control tumors." (PMID 30355451, 2018). "For example, IRF9, transcription factor, participates in the signaling transduction pathway of type 1 interferon, serving as a cancer suppressor." (PMID 27421136, 2016). "Three out of the six most significant canonical pathways were related to the cancer suppression or prevention, namely Interferon Signaling (IRF9, IFIT3), BER pathway (XRCC1) and DNA Double-Strand Break Repair by Non-Homologous End Joining (XRCC1)." (PMID 27421136, 2016).
cancer (continued). "Additionally, the increase in IRF9 expression post-treatment was strongly correlated with drug responsiveness across nine cancer types, possibly due to cell death effects, such as apoptosis through the activation of caspase." (PMID 39062738, 2024). "Yet, a direct role for USP18 in transcription regulation has not been reported, but it might form a complex with STAT2/STAT1/IRF9 to enhance expression of ISGs in cancer cells." (PMID 37002195, 2023). "However, so far, little is known about the regulation of IRF9 expression, both in immune cells and cancer tissues." (PMID 35244540, 2022). "Therefore, we performed a functional knockdown screen of 92 cancer associated transcription factors and identified GATA3, SPDEF, IRF9, and YY1 as candidate transcriptional activators/repressors for APOBEC3B gene expression." (PMID 32934779, 2020). "However, a significant correlation of JAK2V617F allele burden and ISG induction was observed for IRF9 (p = 0.0492), suggesting that IRF9 expression reflects the malignant tumor burden in PV." (PMID 30940163, 2019). "We compared the distribution of patient characteristics: cancer stage, histological grade, sex, and age, partitioned across four sub-groupings based on TGFB2 and IRF9 mRNA expression levels and TGFB2 and IFI27 mRNA expression levels." (PMID 39457004, 2024). "We confirmed the activation of IFN‐I signaling in cancer cells with MSC‐DC, as reflected by increased phosphorylation of STAT1 and STAT2 and increased IRF9 expression, which was reduced by Gap26." (PMID 38638003, 2024). "Specifically, IRF9 and XRCC1 were highly expressed in the tumors from PsP patients and both of them are involved in cancer suppression and prevention." (PMID 27421136, 2016). "In summary, we show that IRF9 protein expression is increased in human PCa and correlates with IL6 expression in cancer areas." (PMID 23913484, 2013). "Moreover, cancer cells often exhibit an increased expression of STAT1/2 and IRF9 for various reasons." (PMID 39062738, 2024). "Although IRF9 is not reported to influence cell cycle progression in cancer cells, the observed changes in CDKN1A expression alterations encourage research focused in this field." (PMID 33430083, 2021). "TEAD-AP1 cooperation with steroid receptor coactivators (SRC) drives downstream gene transcription to regulate cancer cell migration and invasion, and STAT1, STAT2 and IRF9 form a heterotrimer that regulates transcription of genes containing IFN-stimulated response elements." (PMID 27899659, 2017). "We then conducted biological relevance analysis for 33 candidate genes to identify the potential biomarkers, i.e., Interferon regulatory factor (IRF9) and X-ray repair cross-complementing gene (XRCC1), which were involved in the cancer suppression and prevention, respectively." (PMID 27421136, 2016). "Although direct evidence connecting IRF9 to BLCA is currently sparse, its function in regulating immune responses and potential interactions with other signaling molecules, such as TRAF5, could offer valuable insights into its role in cancer progression." (PMID 40893939, 2025). "Similarly, the extensive overlap among the Irf9, Stat1 and Nfyc regulons underscores their prevalent cofactorship and indicates that MC38-FUT9 cells display decreased expression of negative regulators of cancer stemness." (PMID 32927726, 2020). "Our results demonstrated that the increased gene expression of IRF9, a member of the IRF/STAT family, serves as a biomarker for the responsiveness to these DNA-damaging chemotherapies and suggest that its suppression may be a mechanism by which cancer cells acquire PARP inhibitor resistance." (PMID 39062738, 2024).
cancer (continued). "Since STAT2 can form a complex with IRF9 and induce the expression of ISGs in the absence of STAT1, which seems to be tissue‐ and context‐dependent, we next silenced STAT2 in CAF1 before adding the CM from treated cancer cells." (PMID 33476079, 2021).
bacterial infections (2 papers, 2019 to 2023). "In addition, a further 12 ISGs of 380 tested ISGs including STAT1, STAT2, JAK1, IRF9, IRF2, IRF7 are key elements of IFN signaling, and classical and well-known ISGs such as ISG15, PKR, MX1, IFIT1, PML, IFI27 play key roles in viral or bacterial infections." (PMID 30717477, 2019).
infectious disease (2 papers, 2023 to 2024). A disorder directly resulting from the presence and activity of a microbial, viral, or parasitic agent in humans. "IRF9 plays a role in the regulation of infectious diseases and autoimmune disorders." (PMID 39596321, 2024).
neurodegenerative disease (2 papers, 2015 to 2017). A disorder of the central nervous system characterized by gradual and progressive loss of neural tissue and neurologic function. "Thus, the down-regulation of STAT1, STAT2, IRF7 and IRF9 through GSK-J4 could inhibit neurodegenerative diseases as well as brain inflammation." (PMID 28747667, 2017). "Thus, the downregulation of Irf1, Irf7, and Irf9 through JQ1 could inhibit neurodegenerative diseases as well as brain inflammation." (PMID 25890327, 2015).
neurological disease (2 papers, 2021 to 2022). "Previously, it was reported for IRF9 knockout mice that type I IFN mediates a potent inflammatory response associated with a more severe neurological disease." (PMID 34676541, 2022). "Another study have reported that IRF9 have a protective function in CNS and its deficiency could trigger severe neurological disease." (PMID 33936086, 2021).
cardiac disease (1 paper, 2024). "Therefore, high expression of IRF9 in the heart of H. bleekeri might suggest it plays roles in maintaining the normal physiological function of the heart in fish and interferon might respond to other pathologies such as cardiac disease besides innate immunity." (PMID 39596618, 2024).
kidney disease (1 paper, 2019). "With respect to ISGF3, in a mouse model of pristane-inducible IFN-driven lupus, both IRF9 and STAT1 were shown to be required for autoantibody production and development of kidney disease." (PMID 30984161, 2019).
respiratory diseases (1 paper, 2023). "IRF9 expression has been related to multiple respiratory diseases and its deficiency is associated with worse outcomes of respiratory viral infections, including SARS-CoV-2." (PMID 37389217, 2023).
IRF9 also shares sentences with these, for which no sentence is quoted: pneumonia (6 papers); neuroblastoma (4); asthma (2); Autoimmunity (2); cardiovascular disease (2); cervical cancer (2); experimental autoimmune encephalomyelitis (2); herpes simplex encephalitis (2); lupus nephritis (2); pulmonary arterial hypertension (2); rheumatoid arthritis (2); triple-negative breast carcinoma (2); viral disease (2); Werner syndrome (2); adenosquamous cell carcinoma (1); anaplastic oligoastrocytoma (1); atherosclerosis (1); autoimmune uveitis (1); bronchioloalveolar carcinoma (1); chlamydial infection (1); chronic hepatitis C (1); CNS tumors (1); Crohn disease (1); cystic fibrosis (1); demyelination diseases of the CNS (1); diabetes (1); Emphysema (1); esophageal squamous cell carcinoma (1); Fanconi anemia (1); fibrosis (1).
A further 26 diseases each share a sentence with IRF9 in 1 paper.